Y_RNA (Y RNA )
Gene: Miscellaneous RNA gene on chromosome 1 (248,029,120 to 248,029,221, forward strand). Ensembl gene ENSG00000200085.
Homologues: Orthologues: macaque Y_RNA (88% identical). Paralogues in human: Y_RNA (93% identical), RNY3 (90% identical), Y_RNA (89% identical), Y_RNA (88% identical), RNY3P1 (87% identical), Y_RNA (87% identical), Y_RNA (86% identical), RNY3P2 (85% identical), Y_RNA (85% identical), RNY3P14 (84% identical), Y_RNA (84% identical), RNY3P16 (83% identical), and 95 more.